STAT3 (signal transducer and activator of transcription 3)
Diseases named in the same sentence as STAT3 in open-access papers (continued):
Sharing a sentence is not in itself a finding about the gene and the disease.
cancer (continued). "Anti-cancer drug discovery efforts to directly inhibit the signal transducer and activator of transcription 3 (STAT3) have been active for over a decade following the discovery that 70% of cancers exhibit elevated STAT3 activity." (PMID 30220975, 2018). "JAK2/STAT3 signaling pathway shows a pivotal role in cancer cell survival and disease progression." (PMID 30356255, 2018). "In addition to its traditional role in cancer cell proliferation, invasion, and migration, STAT3, as a transcription factor, promotes cancer development by altering the expression of other genes in cancer cells." (PMID 29329543, 2018). "Several studies have shown that STAT3 regulates the EMT process in many types of cancers." (PMID 30551687, 2018). "To further detect MSC-CM could sensitize cancer cells to radiotherapy via inhibiting Stat3 signaling pathway, we used Stat3 inhibitor Stattic to inhibit the Stat3 signaling pathway and then analyzed the radiosensitivity of cancer cells affected by MSC-CM." (PMID 30297887, 2018). "The activated STAT3 has oncogenic roles in many cancers, including GBC." (PMID 30086773, 2018). "STAT3 protein facilitates oncogenic signalling by mediating the overexpression of anti-apoptotic proteins Bcl-xL and Mcl-1, which in turn promote cell proliferation in cancers." (PMID 30274155, 2018). "Besides other functions, STAT3 is an important regulator of normal stem cells and cancer stem cells." (PMID 29588647, 2018). "In addition, a crosstalk between STAT3 and Wnt activates the Wnt/β-catenin signaling pathway, which is also responsible for cancer stemness." (PMID 30068339, 2018). "APE1/Ref-1 is a multifunctional protein that was initially discovered as an enzyme in the base excision repair (BER) pathway, but has also emerged as a redox-signaling regulator of a number of transcription factors known to be involved in cancer, namely NFĸB, AP-1, HIF1a, and STAT3." (PMID 29541389, 2018). "STAT3 plays an important role in liver inflammation and cancer." (PMID 30197639, 2018). "Napabucasin is a STAT3 inhibitor with anti-tumor activity in vitro and in vivo in various cancers." (PMID 30551640, 2018). "Like STAT3, TP63 is rarely mutated in human cancer, but p63 activity is often increased." (PMID 29588647, 2018). "However, despite the reported evidence that HDAC inhibitors inhibit STAT3 activation through abolishing STAT3-phosphorylation at Tyr705 in pathological conditions such as cancer and kidney fibrosis, the exact mechanism remains elusive." (PMID 30481203, 2018). "Taken together, these data suggest that the increased acid production in cancer cells increases the amount of lysosomal STAT3, which in turn enhances the proton pumping activity of the V-ATPase thereby possibly assisting in the maintenance of alkaline cytosol in spite of increased acid load." (PMID 30127373, 2018). "Mechanistic studies showed that inhibition of p-STAT3 within the mouse cancer cachexia model with C188-9 treatment reduced transcript levels of muscle-specific ubiquitin ligases MAFbx/Atrogin-1 and MuRF1 and improved protein synthesis in muscles of mice bearing tumors." (PMID 30081609, 2018). "Since STAT3 was known to function as nuclear transcription factors by directly interacting with the promoter of its target genes and thereby contributing to start transcriptional activation in cancer." (PMID 30591689, 2018). "A number of miRNAs have been identified that affect STAT3 signaling in various types of cancers." (PMID 29588647, 2018). "Other STAT3 inhibitors are currently used for targeting the STAT3 pathway in cancer, including GBM." (PMID 29423098, 2018). "Our findings indicated that STAT3 could be a cancer-promoting factor and potentially a significant prognostic factor in UTUC." (PMID 30091994, 2018). "The patients with tumors showing high STAT3 expression had a significantly higher risk of both disease progression (p = 0.009) and cancer-specific mortality (p = 0.009), but not with tumors expressing S1PR1 or IL-6." (PMID 30091994, 2018).
cancer (continued). "In addition, STAT3 has been widely recognized as an oncogene in various cancers and has been confirmed to be constitutively active in TNBC." (PMID 30473665, 2018). "Therefore, we have proposed that the critical mechanism through which emodin sensitizes HCC cells to the anti-cancer effects of sorafenib is the suppression of AKT and STAT3 oncogenic growth signaling caused by decreases in intracellular cholesterol." (PMID 30321984, 2018). "Moreover, STAT3 (-1.83), EphA2 (-1.74) and BMP7 (-47.17), all proteins involved in signalling pathways associated with cancer stem cell activities, were also found to be down-regulated in the proteomics datasets." (PMID 29568355, 2018). "Giving its wide use in traditional medicines with low toxicity and few adverse reactions, it is conceivable that curcumin might be further explored as a unique STAT3 inhibitor for anti-cancer therapies." (PMID 30518397, 2018). "However, specific cancer cell genetics can alter the outcome of STAT3 signaling, as observed independently in subsets of glioma and prostate tumors." (PMID 29921770, 2018). "Such evidence differentiates STAT3 cellular localization from other STAT molecules and identifies a feature that could be targeted for clinical intervention in patients with STAT3-dependent cancers." (PMID 29914167, 2018). "Importantly, the anti-cancer effect of P-V seemed to depend solely on inhibition of the actions of mitochondrial STAT3." (PMID 29914167, 2018). "Several studies have shown that blocking STAT3 sensitizes cancer cells to apoptotic stimuli." (PMID 29921768, 2018). "The anticancer effects of oleandrin and odoroside A might be due to the suppression of phospho-STAT-3-mediated pathways that are involved in the regulation of invasion-related molecules, such as cancer stem cell markers and EMT-related proteins." (PMID 30373171, 2018). "Thus, STAT3 plays a key role in the pathogenesis of many cancers, lymphocyte differentiation and innate immune response." (PMID 32201498, 2018). "STAT3 plays a vital role in regulating the expression of various downstream genes that control stress response, immune function, inflammation, and metastasis of cancer." (PMID 28661045, 2018). "The JAK/STAT3 pathway has emerged as an attractive target for cancer treatment." (PMID 29849942, 2018). "In addition, overexpression of Src in cancer accelerates metastasis and is responsible for chemoresistance via multiple downstream signaling pathways, concerning Akt, MAPKs, STAT3, cytokines, etc.." (PMID 30322180, 2018). "STAT3 has been proposed to regulate miRNA expression through positive and negative feedback loops and in doing so impact many processes important to development and pathogenesis, including various cancers." (PMID 30603058, 2018). "As Asrij activates STAT39 and OCIAD2 is implicated in several cancers where STAT3 is active, we checked for any functional homology between the OCIAD proteins by testing the ability of different regions of OCIAD2 to bring about STAT3 activation." (PMID 29743632, 2018). "STAT3 is well-recognized as an oncogenic driver in cancer including GBM." (PMID 29774125, 2018). "The exogenous expression of PTPRD in human GBM and other cancer cell lines inhibited cell growth, which coincided with a substantial decrease in the expression levels of phosphorylated STAT3 (Y705) and, consequently, one of its downstream targets, suppressor of cytokine signaling 3 (SOCS3)." (PMID 30208623, 2018). "Furthermore, phosphorylated STAT3 was found to translocate to the nucleus of BMDMs in response to incubation with cancer-derived exosomes." (PMID 29867925, 2018).
cancer (continued). "Therefore, STAT3 inhibition has become an attractive target for cancer therapy, because it has a strong potential to offer broader clinical impact." (PMID 29899697, 2018). "Numerous studies have found that Stat3 activation is involved in regulating radioresistance of cancers, which could be due to its central roles in CSC maintenance." (PMID 30297887, 2018). "STAT3 is commonly activated in a variety of human cancers, including HCC." (PMID 30618745, 2018). "Beyond JAK3-mediated STAT3 phosphorylation, epigenetic silencing of negative regulators such as PTPN6 may contribute towards sustained STAT3 phosphorylation in cancer cells." (PMID 30420593, 2018). "Very recent data, however, reported a positive outcome from the use of silibilin, a molecule that impairs STAT3 activation via direct interaction with STAT3, in cancer patients with brain metastases expressing high levels of STAT3 activation in reactive astrocytes surrounding the cerebral lesion." (PMID 30231553, 2018). "Although the oncogenic roles of STAT3 are well known, the roles of IL-11 in cancer are relatively unknown." (PMID 30086773, 2018). "STAT3 has been proved to participate in the generation and development of various cancers." (PMID 29423040, 2018). "It was found that MSC-CM could inhibit the level of activated Stat3, suppress cancer growth, and exhibit synergetic effects with radiation treatment in vitro and in vivo." (PMID 30297887, 2018). "Therefore, an additional level of caution is needed when designing strategies targeting Jak/STAT3 signaling in cancer cells." (PMID 29921770, 2018). "In addition, STAT3/NF-κB1 signaling pathways play important roles in promoting the development and progression of several cancers and also in controlling the immune response." (PMID 30208630, 2018). "Moreover, various studies demonstrated that STAT3 enhances the cancer cells’ ability to invade and metastasize in response to integrating the signals from multiple extracellular stimuli." (PMID 30002310, 2018). "So targeting Stat3 could be a therapeutic potential in cancers or wherever immunosuppression is harmful." (PMID 30555467, 2018). "This makes STAT3 an attractive therapeutic target for cancers." (PMID 29914167, 2018). "Recent studies suggest that Stat3 plays a central role in development of cancer radioresistance." (PMID 30297887, 2018). "Furthermore, it has been shown that post-translational modification of PTPRT by glycosylation reduces its activity by causing it to dimerize, which has been shown to result in enhanced cancer cell migration via the activation of STAT3-mediated signaling." (PMID 30208623, 2018). "More recently, Meads and collaborator demonstrated that PYK2 is positioned upstream of JAK1/STAT3 signaling and that it is a critical mediator of a novel survival pathway activated in the context of co-stimulation of cancer cell and the microenvironment through especially IL-6." (PMID 29455640, 2018). "Since there is evidence that AP-1 and STAT3 act synergistically to boost aggressiveness of cancer cells, AP-1 and STAT3 may cooperate to maintain such a loop." (PMID 30344941, 2018). "Cytokine/growth factor-activated Src and STAT3 have been linked with promotion of EMT, migration, invasion, and angiogenesis in cancer cells, through induction of STAT3 downstream metastasis-associated proteins, including mucin 1 (Muc1), VEGF, and CXCR4, and by microtubule stabilization." (PMID 30149591, 2018). "STAT3 is an important transcription factor that regulates the processes of proliferation and apoptosis, and persistently activates in a high number of human cancers." (PMID 29867489, 2018). "In all, STAT3 upregulates Slug to activate cancer motility and invasion in GBM cells." (PMID 30551687, 2018).
cancer (continued). "Working with two small drug-development companies (StemMed, Ltd, Houston, USA and Tvardi Therapeutics, Inc., Houston, TX, USA), we developed an oral small-molecule STAT3 inhibitor (C188-9) that binds to STAT3 with high affinity and achieves excellent exposure in cancer patients in Phase I studies." (PMID 30081609, 2018). "Furthermore, parthenolide inhibited the IL-6-induced cancer cell migration and preferentially inhibited the growth of cancer cells that had constitutively activated STAT3." (PMID 29921758, 2018). "STAT3 distribution and functional status in cancer cells can be modulated by acetylation." (PMID 29914167, 2018). "The advantages of targeting STAT3 in cancer therapy have been fully investigated." (PMID 30186159, 2018). "JAK2/STAT3 seem to be the most popular targets in cancer treatment." (PMID 30109213, 2018). "Since, the proteasome affects so many pathways (ubiquitin-proteasome, Toll-like, STAT3) present data have revealed that some of these proteasome activators may be useful in several types of cancer patients and other inflammatory diseases." (PMID 29606130, 2018). "The excessive activation of STAT3 signaling pathway has been found in many cancers, including GBC." (PMID 30086773, 2018). "Of interest, the impairment of Shingosine kinases had also a slight effect on STAT3, suggesting that this axis may be critical to control essential processes in chronic inflammation and cancer through STAT3." (PMID 30185808, 2018). "Both STAT3 and NFκB are constitutively activated in many cancers." (PMID 30250641, 2018). "However, it should be noted that in addition to centrosomal activities, STAT3 inhibitors significantly inhibit cancer stem cell gene regulation." (PMID 29757235, 2018). "STAT3 inhibition has been mainly explored as a way to reduce survival of cancer cells." (PMID 29566069, 2018). "There is precedence, in the case of STAT3, for the development of cancer, mostly large granular lymphocytic (LGL) leukemias, with somatic gain of function mutations, with much less manifestation of malignancies in patients harboring the same mutations in germline cells." (PMID 30344948, 2018). "In addition, STAT3 plays a key role in and is upstream of many of the functions that CT affects and is a known target of CT in other cancers." (PMID 30157799, 2018). "The activation of STAT3 augments the expression of numerous genes, such as Bcl-xL, Mcl-1, cyclin D1, and vascular endothelial growth factor, which could enhance cancer cell survival or proliferation." (PMID 30302278, 2018). "The aberrant activation of STAT3 contributes to several human diseases, particularly cancer." (PMID 30208623, 2018). "Hence, the inhibition of STAT3 signaling has been suggested to be a viable therapeutic approach for cancers." (PMID 30109144, 2018). "Therefore, we used cBioPortal to identify human cancers discovered significant CAN in the STAT3-gene signature." (PMID 29423040, 2018). "However, future research is required to validate our findings and thus promote the clinical utility of STAT3 in those cancers prognosis evaluation." (PMID 29423040, 2018). "STAT3 and NF-κB synergistically function to give cells the characteristics of cancer." (PMID 30400136, 2018). "STAT3 phosphorylation is necessary to activate the acute phase response protein gene expression in the liver, which is a generalized response to insults (i.e., cancer) by the innate immune system." (PMID 30072615, 2018). "The GIV protein (Gα-interacting vesicle-associated protein, also known as Girdin) modulates the crucial signaling pathways in processes including macrophage chemotaxis, wound healing, and cancer metastasis and can be a target of STAT3 activation in NSCLC cell lines." (PMID 29675018, 2018). "The deregulation of STAT3 pathway is involved in various diseases, including many types of cancer." (PMID 29443735, 2018).
cancer (continued). "STAT3, another transcription factor involved in cancer development, is constitutively activated in cancer cells from various tissues and the results of several studies suggest a direct contribution of STAT3 to malignant progression through survivin signaling." (PMID 29587347, 2018). "The link between PLCγ1 activity and the IL-6/STAT3 signaling pathway could account for the transcription of many important cancer-related genes." (PMID 29464031, 2018). "To validate further our hypothesis that TESC/c-Src/IGF1Rβ complex mediates the activation of STAT3 and the expression of ALDH1, a core regulator of cancer stemness, we suppressed STAT3 activation via STAT3 inhibitor VII or siRNA." (PMID 30013043, 2018). "It is established that Stat3 is essential in the maintenance of stem cells and cancer stem cells." (PMID 30026553, 2018). "There is currently strong evidence to suggest that aberrant activation of signal transducer and activator of transcription 3 (STAT3) represents a key step in the neoplastic process in human cancers through the induction of anti-apoptosis, cell proliferation, angiogenesis, invasion, and metastasis." (PMID 29899697, 2018). "Among all Stats, Stat3 plays a very crucial role in incidence of cancers." (PMID 30555467, 2018). "STAT3, signal transducer and activator of transcription 3, is a key component in several signalling pathways, is over-activated in approximately 70% of cancers and plays critical roles in cell proliferation, cell survival, angiogenesis, immune invasion and metastasis." (PMID 30220975, 2018). "However, a recent study was able to generate sorafenib derivatives that more effectively activate SHP1 activity and, thereby, inhibit STAT3 activation and suppress cancer cell growth to combat tumorigenesis and chemoresistance." (PMID 30208623, 2018). "Importantly, it has been described that both MMPs and STAT3 are involved in the hnRNP A2/B1-related cancer metastasis." (PMID 29547514, 2018). "EGF significantly induced STAT3 phosphorylation and elevated the mRNA levels of LGR5 in the HT29 cells, implying that addition of EGF activated STAT3 in the cancer stem-like tumorspheres, thus contributing to the formation and survival of EGFR-positive CRC stem-like tumorspheres." (PMID 30068339, 2018). "Furthermore, STAT3 inhibition has been shown to prevent cell proliferation and induce apoptosis in several cancer cell types." (PMID 30594131, 2018). "Constitutive activation of STAT3 is frequently found in cancers including GBM." (PMID 29423098, 2018). "In NetworkAnalyst analysis, KEGG associated with cancer pathways showed that PDGFA was indicative and STAT3 may be involved in activating the formation of cancer stem-like tumorspheres." (PMID 30068339, 2018). "Moreover, inflammatory cells and cytokines demonstrably support cancer stem cells via the IL-6/STAT3 pathway." (PMID 30104473, 2018). "Therefore, inhibition of STAT3 activation represents a potential therapeutic approach for human cancers." (PMID 30618745, 2018). "Additionally, EMT-inducing transcription factors, whose activity is activated by STAT3, promote the metastasis of cancer cells to distant organ sites." (PMID 28157698, 2017). "Taken all together, the up-regulation of Cdk5 is a result of DNA damage stimulation and in turn induces DNA repair through STAT3-mediated up-expression of Eme1, which may confer cancer cells resistance to chemotherapy treatment." (PMID 28288624, 2017). "Interestingly, IL-6 is known to activate STAT3 which in turn interacts with NF-κB to form ReLA survival complex that gives the radio resistant property to cancer cells." (PMID 29070894, 2017). "Compounds KI12 and KI16 showed a good selectivity profile further suggesting that these are promising inhibitors of STAT3 signaling and may have activity as potential cancer therapeutic agents." (PMID 28636670, 2017). "Aberrant activation of STAT3 was reported to promote cancer progression in many human cancers." (PMID 28750624, 2017).